IL1RL1 (interleukin 1 receptor like 1)
Diseases named in the same sentence as IL1RL1 in open-access papers (continued):
Sharing a sentence is not in itself a finding about the gene and the disease.
lung carcinoma (continued). "Several reports on IL1RL1 down-regulation in lung cancer also validates our findings in this study." (PMID 31973134, 2020). "However, another study reports downregulation of IL33 and IL1RL1 in human lung cancer tissue and cells, compared to normal tissue and cells." (PMID 28119694, 2016). "Furthermore, the authors found that IL33 and IL1RL1 transcript levels were inversely correlated with stages of human lung cancers and overall survival." (PMID 28119694, 2016). "Moreover, bioinformatics analysis results revealed that the expression level of IL1RL1 was significantly different between normal and LUAD and LUSC tissues, and there were significant differences between six SNPs in IL1RL1 and the expression level of IL1RL1 in lung cancer tissues." (PMID 37719702, 2023). "The upregulated genes included CYP4F3, IL1RL1, PTGS2, and CXCL8, which are related to inflammation; HKDC1, MYEF2 and CYP1A1, which are related to hepatocarcinoma or lung carcinoma; and SLC7A11 and NEFM, which are related to neuronal damage." (PMID 33247188, 2020). "However, this study did not explore the specific mechanism of IL1RL1 in the occurrence and development of lung cancer." (PMID 37719702, 2023).
allergic rhinitis (5 papers, 2016 to 2024). Inflammation of the nasal mucous membranes caused by an IgE-mediated response to external allergens. "IL1RL1 polymorphisms rs72823628, rs950881 and rs3771175 were found to be associated with a reduced risk of allergic rhinitis risk in the Chinese Han population." (PMID 37719702, 2023). "Besides, KLF4 regulates immune response-related genes including IL1RL1, CD274, and CD44 in human nasal epithelial cells of allergic rhinitis." (PMID 38245772, 2024).
colitis (5 papers, 2020 to 2025). Inflammation of the colon. "In order to elucidate the functional impact of the shift in Il1rl1 transcript usage associated with DSS colitis, we have computed isoform-specific expression from RNAseq data by measuring the counts associated with the exons specific to either isoform." (PMID 36694043, 2023). "As with Il1rl1, the sashimi plot reveals that the differential exon-usage pattern arises from overexpression of a short transcript (Refseq IDs: XM_006525689.3 or XM_006525690.2) in colitis." (PMID 36694043, 2023). "One preclinical study showed that blocking the IL-33/suppression of tumorigenicity 2 (ST2, also known as IL-1RL1) signaling axis enhances mucosal healing in DSS- and 2,4,6-trinitrobenzene sulphonic acid (TNBS)-induced colitis in mice." (PMID 40869366, 2025). "Several genes such as Gata3, Itk, Ccl8, Ccl22, Ccr4, Crlf2, Il9r, Il1rl1, and Arg2 are regulated concordantly in T-cell transfer colitis, acute DSS colitis and the time point representing high inflammation in the DSS time course." (PMID 34136502, 2021).
leukemia (5 papers, 2019 to 2025). A malignant (clonal) hematologic disorder, involving hematopoietic stem cells and characterized by the presence of primitive or atypical myeloid or lymphoid cells in the bone marrow and the blood. "Loss of Il1rl1 in LSCs from Il1rl1f/f Mx1Cre mice decreased the total BM leukemia burden and leukemic cells proliferation vs Il1rl1f/f LSCs transplanted mice at day 14 and 21 post-challenge following pIpC injection." (PMID 40659660, 2025). "Loss of Il1rl1 in established leukemia also prolonged survival of Il1rl1f/f Mx1Cre mice compared with control mice, this model better mimics potential therapeutic interventions of targeting Il1rl1." (PMID 40659660, 2025). "In fact, we found that CSF2RB− IL1RL1+ cells showed significantly impaired colony-forming ability when grown in vitro, despite their robust ability to cause leukemia when transplanted into recipient mice." (PMID 30742053, 2019). "Tertiary transplantations of Il1rl1−/− LSCs continued to show a delay in leukemia growth and an improved survival versus WT LSCs." (PMID 40659660, 2025). "Mice transplanted with IL1RL1-deficient MOLM14 cells exhibited prolonged survival and lower leukemia burden compared to WT MOLM14 recipients at day 10 and 21 post-challenge." (PMID 40659660, 2025). "Similar to findings in the MLL-AF9 leukemia model, we observed that Il1rl1+Foxp3+ Tregs were significantly reduced in the spleen and liver of BC281-treated mice compared to those receiving BC462." (PMID 40659660, 2025). "The observation that patients with high IL1RL1 expression exhibit lower survival rates in comparison to those with low IL1RL1 expression prompted us to investigate its expression in different molecular genetic subtypes of leukemia such as MLL-AF9 fusion." (PMID 40659660, 2025). "Il1rl1−/− LSC recipients also showed reduced leukemia burden during disease progression compared to WT LSC recipients." (PMID 40659660, 2025). "Using a knock-in mouse model of inversion AML, we previously demonstrated that the fusion gene, Cbfb-MYH11, induces the expression of IL-33 receptor, IL1RL1, on leukaemia cells." (PMID 34435521, 2021). "Previously, we showed that IL1RL1, the receptor of IL-33, is highly expressed in leukemia cells expressing Cbfb-MYH11, and exogenous treatment with IL-33 promoted the survival of both primary mouse leukemia cells and human AML cell lines in vitro." (PMID 33324412, 2020). "Further investigation revealed that the IL-33/IL1RL1 axis can inhibit leukemia cell apoptosis via phosphorylation of p38 MAPK." (PMID 33324412, 2020). "Collectively, our results indicate that IL1RL1 is dynamically expressed in Cbfb-MYH11+ leukemia cells and promotes their survival." (PMID 30742053, 2019). "Based on these findings, we propose that IL1RL1 cell surface expression is dynamic and contributes to leukemia cell survival." (PMID 30742053, 2019). "The expression of IL1RL1 (the gene encoding receptor for IL33), which was reported co-expressed with RUNX1 in mouse and human leukemia cells, was also positively correlated with that of RUNX1." (PMID 31501518, 2019). "In the present study, we show that expression of the leukemogenic fusion gene Cbfb-MYH11 induces expression of IL1RL1 prior to CSF2RB, implying that IL1RL1 marks an earlier stage of leukemia development." (PMID 30742053, 2019). "To test this possibility, we examined if there is a difference in the response between IL1RL1+ and IL1RL1− leukemia cells to DOXO in vivo." (PMID 30742053, 2019). "With the exception of CSF2RB− IL1RL1− KIT− cells, we found that each sub-population caused leukemia at both the 1,000 and 10,000 cell doses, indicating that each of these sub-populations contains LSCs." (PMID 30742053, 2019). "The duality of Il1rl1 targeting, of leukemic stem cells (seed) and the inhibitory immune cells in the microenvironment (soil), represents a novel approach to treating one of the least curable leukemias in man." (PMID 40659660, 2025).
leukemia (continued). "In this study, we investigated how stem cell leukemogenesis is initiated and maintained and we hypothesized that a stress-induced intrinsic IL-33/Il1rl1 autocrine loop will initiate and promote leukemia stemness." (PMID 40659660, 2025). "Interestingly, frequencies and absolute number of Il1rl1+ Tregs were decreased in the BC281-treated group vs BC462 control in the MLL-AF9 leukemia model." (PMID 40659660, 2025). "Furthermore, we found that IL1RL1 expression in human HSCs in steady state is nearly undetectable and much lower as compared to LSCs in the leukemia niche." (PMID 40659660, 2025). "Overall, these findings indicated that anti-Il1rl1 T-BsAb using murine antibodies in an immunocompetent model and humanized antibodies in a human xenograft model effectively inhibit both leukemia growth and the tolerogenic immune microenvironment in immunocompetent and humanized pre-clinical models." (PMID 40659660, 2025). "Moreover, in accordance with the upregulated IL1RL1 on leukaemia cell surface, we observed a remarkably increased serum IL-33 level in primary ALL patient samples in comparison to HD." (PMID 34435521, 2021). "In fact, the dynamic expression of KIT and IL1RL1 in leukemia cells suggests that these receptors may be regulating cell processes other than differentiation." (PMID 30742053, 2019). "To determine whether IL1RL1 continues to be expressed in the LSC-enriched CSF2RB− population after leukemic transformation, we stained leukemia cells isolated from Cbfb+/56M, Mx1-Cre+ mice for IL1RL1 and KIT." (PMID 30742053, 2019). "We found that the CSF2RB− IL1RL1+ KIT+ population had the highest BrdU incorporation rate, which correlated with the fastest leukemia development after transplantation." (PMID 30742053, 2019). "We observed that the expression of CSF2RB, IL1RL1, and KIT in recipient leukemia samples was similar to that of the original, donor leukemia samples, regardless of the sub-population transplanted." (PMID 30742053, 2019). "To determine the role of Il1rl1 in leukemia maintenance, we established primary leukemia in immunocompetent mice by injecting 103 LSCs from Il1rl1f/f Mx1Cre or Il1rl1f/f MLL-AF9GFP and waited 4 days for the leukemia to be engrafted." (PMID 40659660, 2025). "To test whether IL1RL1 and KIT can be used to isolate cells with LSC activity in vivo, we performed LDA using leukemia samples from three independent Cbfb-MYH11 expressing mice." (PMID 30742053, 2019). "Mice transplanted with CSF2RB− IL1RL1− KIT− cells had the longest time to leukemia development and the lowest penetrance with statistically significant differences in survival as compared to mice transplanted with CSF2RB−, IL1RL1−, KIT+/− cells at the 10,000 cell dose." (PMID 30742053, 2019). "Thus, in this report we examined the expression of IL1RL1 in the LSC-enriched CSF2RB− population, and the effect of the IL1RL1 ligand, IL-33, on Cbfb-MYH11 expressing leukemia cells." (PMID 30742053, 2019). "Mice transplanted with the CSF2RB− IL1RL1+ KIT+ cells showed the shortest average life span and highest penetrance of leukemia development with statistically significant differences in survival as compared to mice transplanted with CSF2RB−, IL1RL1−, KIT+/−, or CSF2RB+ cells at the 10,000 cell dose." (PMID 30742053, 2019). "To examine if IL1RL1 could be a marker for less differentiated leukemia cells, we characterized the expression of IL1RL1 after induction of Cbfb-MYH11 but before leukemia development." (PMID 30742053, 2019). "Our finding that all LSC sub-populations recapitulate the heterogeneity of the original leukemia sample implies that the sub-populations defined by CSF2RB, IL1RL1, and KIT are likely not to be organized in a strict hierarchical differentiation scheme." (PMID 30742053, 2019).
Myocardial fibrosis (5 papers, 2020 to 2025). "Further, physical inactivity was associated with elevated plasma levels of Metalloproteinase inhibitor 4, Soluble interleukin 1 receptor-like 1, Elafin and Transferrin receptor protein 1, which are implicated in myocardial fibrosis, migration and apoptosis." (PMID 35265689, 2022). "Patients with LOY >17% showed significantly higher plasma levels of soluble interleukin 1 receptor-like 1, a biomarker for myocardial fibrosis." (PMID 39005209, 2024). "Interaction between IL-33 and IL1RL1 in experimental models results in the reduction of myocardial fibrosis and apoptosis and the improvement of cardiac function." (PMID 31924244, 2020). "Moreover, IL-33/IL1RL1 signaling could activate TGF-β-mediated fibroblast activation and epithelial-mesenchymal transition in the myocardium, promoting extracellular matrix (ECM) production, thereby driving myocardial fibrosis and structural remodeling characteristic of HCM." (PMID 40599543, 2025).
psoriasis (5 papers, 2015 to 2023). An autoimmune condition characterized by red, well-delineated plaques with silvery scales that are usually on the extensor surfaces and scalp. "In this study, we verified the psoriasis susceptibility genes IFIH1 (2q24.3), ERAP2 (5q15), IL18R1 (2q12.1), LTBR (12p13.31), IL1RL1 (2q12.1), CARD14 (17q25.3), and SLC9A4 (2q12.1)." (PMID 36425068, 2022). "Other validated psoriasis susceptibility genes were ERAP2 (5q15), IL18R1 (2q12.1), LTB (12p13.31), IL1RL1 (2q12.1), CARD14 (17q25.3), and SLC9A4 (2q12.1)." (PMID 36425068, 2022).
rhinitis (5 papers, 2013 to 2023). An inflammation of the mucous membrane lining the nose, usually associated with nasal discharge. "We found that most of the immune- and cytokine-related signatures were significantly altered between AR1 and AR2, revealing a gradual increase in the expression of top genes and rhinitis marker genes (e.g., IL1RL1, CD274, and CD44) from healthy controls to AR1 and then AR2." (PMID 37206297, 2023). "IL4, IL13, IL1RL1, IL18R1 and TSLP are also the only proteins found to be common to eczema and rhinitis." (PMID 28598986, 2017).
ulcerative colitis (5 papers, 2010 to 2025). An inflammatory bowel disease involving the mucosal surface of the large intestine and rectum. "The ‘IL-33 and its receptor IL1RL1 axis’ has been associated with inflammation and stimulation of the Th2 immune response in ulcerative colitis where levels of IL-33 are significantly increased." (PMID 35576023, 2022). "We evaluated the association of six SNPs in IL-33 and IL1RL1 genes, in 805 Crohn’s disease (CD), 816 ulcerative colitis (UC), and 752 controls, using Taqman." (PMID 23634226, 2013). "There was an increase in soluble IL1RL1 levels in the gut, which was mainly associated with the active state of ulcerative colitis, indicating a possible negative regulation of the IL1RL1/IL33 pathway in order to dampen the inflammation." (PMID 21629437, 2010). "Association of IL-33 and IL1RL1 genes markers with ulcerative colitis (UC); case-control study." (PMID 23634226, 2013). "IL1RL1 variants are associated with increased risk of IBD, and one of its variants regulates sST2 expression induced by corticosteroids in ulcerative colitis." (PMID 41010012, 2025).
chronic obstructive pulmonary disease (4 papers, 2010 to 2025). A chronic and progressive lung disorder characterized by the loss of elasticity of the bronchial tree and the air sacs, destruction of the air sacs wall, thickening of the bronchial wall, and mucous accumulation in the bronchial tree. "Recent human data in Chronic Obstructive Pulmonary Disease (COPD) seem to indicate an involvement of soluble IL1RL1 in the early stages of COPD." (PMID 21629437, 2010). "This is further supported by clinical efficacy data for antibodies to IL-33 and its receptor serum-stimulated 2 (ST2; also named IL1RL1 and IL1R4) that have provided clinical precedence for targeting IL-33 in chronic obstructive pulmonary disease (COPD) and asthma." (PMID 37330528, 2023).
eczema (4 papers, 2016 to 2024). "Members of this family are abundantly expressed in the skin, and IL1RL1 is involved in Th2 responses and is important for the pathogenesis of eczema." (PMID 28598986, 2017).
influenza infection (4 papers, 2018 to 2024). "Both interleukin-10 (Il10), a regulatory cytokine associated with decreased immunopathology during influenza infection, and interleukin-1 receptor like 1 (Il1rl1), the receptor for the alarmin IL-33 that alerts of epithelial trauma, were down-regulated in obese ferrets compared to control." (PMID 38728395, 2024). "In contrast, the influenza-induced recruitment of mast cell progenitors to the lung occurred independently of either TLR3 or ST2, as demonstrated using Tlr3−/− or Il1rl1−/− mice." (PMID 30337928, 2018). "However, in the present study both Tlr3- and Il1rl1-deficient mice had an intact recruitment of MCp to the lung in response to the influenza infection and blocking the IL-33/ST2 pathway in Tlr3−/− mice could not either abrogate the influx." (PMID 30337928, 2018).
Sepsis (4 papers, 2017 to 2022). Sepsis is defined as life-threatening organ dysfunction caused by a dysregulated host response to infection. "We demonstrated that deficiency of either Il-33 or Il1rl1 prevented ILC2 expansion in the lungs following sepsis." (PMID 29511181, 2018). "Although sepsis-surviving Il1rl1−/− mice had higher production of IL-33 than WT mice, they failed to produce more IL-4 and IL-13 in the lungs compared to the naive control mice at day 15 after CLP." (PMID 28374774, 2017). "Accordingly, IL-4 stimulation induced higher STAT6 phosphorylation in peritoneal macrophages from sepsis-surviving WT mice than that observed in the macrophages from naive mice, an effect that was abrogated in macrophages from sepsis-surviving Il1rl1−/− mice." (PMID 28374774, 2017). "Intriguingly, Il1rl1−/− mice that survived from sepsis were more resistant to a subsequent challenge infection with L. pneumophila." (PMID 28374774, 2017). "Moreover, production of IGF-1 protein in the lung was also reduced in the lungs of sepsis-surviving Il1rl1−/− or Stat6−/− mice." (PMID 28374774, 2017). "However, ILC2s were significantly reduced in the lungs of sepsis-surviving Il1rl1−/−mice compared to WT mice." (PMID 28374774, 2017). "Importantly, macrophages recovered from sepsis-surviving Il1rl1−/− and Stat6−/− mice harboured significantly fewer bacteria than macrophages from sepsis-surviving WT mice, showing the key role of ST2 and STAT6 in the impaired bactericidal activity of the macrophage from sepsis-surviving mice." (PMID 28374774, 2017). "However, both Il-33−/− and Il1rl1−/− mice exhibited reduced levels of IL-9 and IL-13 in plasma and bronchoalveolar lavage fluid (BALF) after sepsis as compared with those in WT mice." (PMID 29511181, 2018). "In contrast, the production of IL-10 in the lungs of Il1rl1−/− and Stat6−/− mice was markedly reduced at day 15 after CLP, suggesting that type 2 cytokines and IL-33 are involved in the production of IL-10 in sepsis-surviving mice." (PMID 28374774, 2017). "However, the frequency and the absolute number of Treg cells were not increased in the spleens of sepsis-surviving Il1rl1−/− or Stat6−/− mice." (PMID 28374774, 2017).
acute myeloid leukemia (3 papers, 2020 to 2025). Acute myeloid leukemia (AML) is a group of neoplasms arising from precursor cells committed to the myeloid cell-line differentiation. "Through the analysis of public datasets and patient samples, we show that elevated IL1RL1 expression correlates with poor prognosis and therapy resistance in acute myeloid leukemia (AML)." (PMID 40659660, 2025). "High IL1RL1 correlates with poor survival in acute myeloid leukemia." (PMID 40659660, 2025). "We have previously reported elevated IL-33 levels in patients with acute myeloid leukaemia (AML) at diagnosis along with upregulated expression of its receptor, interleukin-1 receptor-like 1 (IL1RL1), as compared to the healthy controls." (PMID 34435521, 2021).
airway hyperresponsiveness (3 papers, 2012 to 2024). "IL-33 and suppression of tumorigenicity 2 (ST2)/IL1RL1 (IL-33 receptor) play a role in allergen-induced eosinophil inflammation, mucus epithelial chemotaxis, and airway hyperresponsiveness and promote Th2 polarization to participate in the immune response." (PMID 39719880, 2024). "This is especially relevant when considering that elevations of circulating IL-33 on HDM stimulation have been reported in mouse models, with attenuated HDM-induced airway hyperresponsiveness in IL1RL1-KO mice." (PMID 32324168, 2020).
allergic asthma (3 papers, 2020 to 2022). A asthma with a basis in a pathological type I hypersensitivity reaction. "The importance of these alarmins in allergic asthma is demonstrated by a recent genome-wide association study (GWAS), which showed that genetic polymorphism in the gene encoding IL-33 or its receptor IL-1RL1 (ST-2) associates closely with the development of allergic asthma." (PMID 36466877, 2022). "When considering the aeroallergen HDM, another relevant environmental agent involved in allergic asthma, our data identified that HBECs release soluble IL1RL1 in response to HDM; however, this response was accompanied by a decrease in membrane IL1RL1 mRNA." (PMID 32324168, 2020).